SGK1 (serum/glucocorticoid regulated kinase 1)
Diseases named in the same sentence as SGK1 in open-access papers (continued):
Sharing a sentence is not in itself a finding about the gene and the disease.
prostate carcinoma (continued). "SGK1 is identified and characterized as a tumor-promoting gene and elevated expression of SGK1 has been observed in several different malignancies, including colon cancer, gastric cancer and prostate cancer." (PMID 29609629, 2018). "SGK1 contributes to androgen-induced growth of prostate cancer cells." (PMID 31225494, 2018). "We investigated the cellular responses to GSK650394 treatment and SGK1 silencing (or overexpression) in human prostate cancer (PCa) cell lines and PC3 xenografts by wound healing assay, migration and invasion assay, western blotting, immunofluorescence and immunohistochemistry." (PMID 29609629, 2018). "Our lead SGK1 inhibitor (5377051) selectively inhibits SGK1 in cultured cardiomyocytes, and inhibits phosphorylation of an SGK1-specific target as well as proliferation in the prostate cancer cell line, LNCaP." (PMID 28336914, 2017). "Thus the lead inhibitor identified blocks SGK1 activity in the LNCaP prostate cancer cell line in addition to primary CMs, thereby providing additional validity of SGK1 as a target of 5377051." (PMID 28336914, 2017). "Furthermore, GSK650394 that functionally inhibits enzymatic activity of SGK1 attenuated androgen-mediated growth of the prostate cancer cell line." (PMID 26491696, 2015). "Furthermore, increased levels of SGK-1 expression have been found in many different tumors such as colon cancer, prostate cancer and non-small cell lung cancer." (PMID 25485633, 2014). "Notably, these findings suggested that E2F2-activated DLEU2 may function as a competing endogenous RNA to facilitate prostate cancer progression by targeting the miR-582-5p/SGK1 axis." (PMID 35075115, 2022). "Our data indicated that overexpression of E2F2 in prostate cancer cells contributed to upregulation of DLEU2, further resulting in aberrant regulation of the miR-582-5p/SGK1 axis." (PMID 35075115, 2022). "Mechanistically, SGK1 induces MTOR signaling to inhibit FOXO3 phosphorylation, leading to a decrease in apoptosis and autophagy in prostate cancer cells." (PMID 35317831, 2022). "To further determine the regulatory mechanism between DLEU2 and SGK1 in prostate cancer, we performed FISH to test subcellular location of DLEU2 in prostate cancer cells." (PMID 35075115, 2022). "Silencing SGK1 inhibits MTOR signaling, providing conditions for FOXO3 phosphorylation, and subsequent induction of apoptosis and autophagy in prostate cancer cells." (PMID 35317831, 2022). "In the section related to prostate cancer metastasis, it was mentioned that SGK1 can mediate autophagy and EMT in prostate cancer cells." (PMID 35317831, 2022). "Furthermore, the SGK1 inhibitor GSK650394 has been shown to induce autophagy and apoptosis in PC3, LNCaP, DU145, and CWR22RV1 prostate cancer cells in vitro." (PMID 32630372, 2020). "Furthermore, SGK1/SGK3 are amplified in up to 3% and 20% of prostate cancer cases, respectively, and SGK1 has been identified as an AR-regulated target gene." (PMID 33105713, 2020). "SGK1 is highly expressed in several tumors, including non-small cell lung cancer, colon cancer, prostate cancer, ovarian tumors, myeloma, and medulloblastoma." (PMID 31225494, 2018). "Mechanistically, DLEU2 promoted serum and glucocorticoid-induced protein kinase 1 (SGK1) expression by acting as an miR-582-5p sponge, and the transcription of DLEU2 was activated by the dysregulation of E2F transcription factor 2 (E2F2) expression in prostate cancer." (PMID 35075115, 2022). "Furthermore, a previous study showed that SGK1 inhibition by GSK650394 could induce G2/M arrest, apoptosis, and autophagy in human prostate cancer." (PMID 34894976, 2022). "Thus, our finding that the polyphenols attenuate SGK1 phosphorylation at Ser422, may suggest a role of the PI3K/mTOR pathway in the mechanism of the cytostatic effect of CUR + CA on prostate cancer cells." (PMID 34679726, 2021).
prostate carcinoma (continued). "SGK1 also regulates cell growth and survival as a downstream effector of PI3K pathway, and it is overexpressed in some types of tumors including colon cancer, medulloblastoma, prostate cancer, ovarian tumors, and non-small cell lung cancer, but not in all tumors." (PMID 26491696, 2015).
diabetes (26 papers, 2008 to 2025). "Furthermore, SGK1 activity has been linked to diabetes through glucocorticoid-mediated inhibition of insulin secretion." (PMID 19461886, 2009). "The SGK1 gene, located on chromosome 6 (6q23.2), encodes serum/glucocorticoid-regulated kinase 1, which has been reported to participate in the development of several human diseases, including cervical cancer, pulmonary fibrosis, Alzheimer’s disease, and type 2 diabetes mellitus." (PMID 39851522, 2025). "Targeting SGK-1 has been shown to reduce the incidence and delay the progression of diabetes, as well as to mitigate the severity of complications." (PMID 40427579, 2025). "In the context of diabetes, SGK1 upregulation has been observed to mediate mesenchymal transformation of vascular smooth muscle cells under hyperglycemic conditions, thereby enhancing medial vascular calcification." (PMID 40427579, 2025). "Myocardial SGK1 and ENaC proteins were significantly decreased in the diabetes+dapa group compared with the diabetes group, and comparable to the control group, when assessed by immunofluorescence techniques (P < 0.001, P < 0.01)." (PMID 36068525, 2022). "The hyperglycemia of diabetes can stimulate Sgk1 expression, augmenting store-operated Ca2+-entry and osteogenic signaling in hAoSMCs." (PMID 35672672, 2022). "A study performed on female rodent model of diabetes demonstrated that the cardioprotective effect of EMPA is mediated through the serum/glucocorticoid-regulated kinase 1 (SGK1) and the epithelial sodium channel (ENaC)." (PMID 35334035, 2022). "SGK1 has recently been considered as a potential drug target for cancer, diabetes, and neurodegenerative diseases." (PMID 32070031, 2020). "SGK-1 transcription is stimulated by excessive glucose levels and diabetes, oxidative stress, DNA damage, ischemia, neuronal injury, and a high-fat diet." (PMID 33083492, 2020). "Taken together, these findings demonstrate that diabetes increases WNK4 phosphorylation at serine residues mediated by SGK1 activity." (PMID 28493961, 2017). "SGK1 mediates diabetes-induced fibronectin production by tubular cells in vitro and Sgk1 knock-out mice made diabetic are relatively protected from the development of renal structural changes." (PMID 24827579, 2014). "Further studies on the role of SGK1 in human insulin secretion and diabetes onset are therefore needed." (PMID 18985156, 2008). "SGK is an attractive candidate gene for type 2 diabetes mellitus onset in humans, as SGK1 exerts pleiotropic effects on glucose metabolism and insulin secretion in various cellular and animal models." (PMID 18985156, 2008). "Recent evidence emphasizes the important role of SGK-1 in diabetes and its complications." (PMID 40427579, 2025). "The current observations expand on the pro-calcific role of SGK1 during high glucose conditions, which could link vascular calcification in the distinct conditions of chronic kidney disease and diabetes mellitus." (PMID 33003561, 2020). "To further corroborate whether diabetes alters the phosphorylation of WNK4 by SGK1, we analyzed the SGK1 expression in the four experimental groups and found that diabetes induces SGK1 expression and SPL significantly prevented these changes." (PMID 28493961, 2017). "Also, co-IP assays showed that diabetes induces the interaction of SGK1 with WNK4, which was prevented by SPL." (PMID 28493961, 2017). "Diabetes increased SGK1 expression and induced its co-immunoprecipitation with WNK4." (PMID 28493961, 2017). "Thus SGK1 contributes to the dysregulation of cellular Na+ and water transport in diabetes mellitus." (PMID 27517916, 2016). "In the present study, since ceramide induces apoptosis by multiple mechanisms in diabetes and its complication such as nephropathy, we aimed to investigate whether SGK-1 may protect even against apoptosis induced by ceramide in kidney cells." (PMID 26379195, 2015).
diabetes (continued). "In conclusion, we demonstrated that in kidney cells, overexpression of SGK-1 is protective against ceramide-induced apoptosis and the role of SGK-1 can be potentially explored as a therapeutic target in conditions like diabetes, where ceramide levels are increased." (PMID 26379195, 2015). "Serum- and Glucocorticoid-inducible Kinase 1 (SGK1) is involved in the regulation of insulin secretion and may represent a candidate gene for the development of type 2 diabetes mellitus in humans." (PMID 18985156, 2008). "Consequently, SGK-1 may serve as a viable target for the development of novel therapeutic regimens for diabetes and diabetic osteoporosis." (PMID 40427579, 2025). "Thus, SGK1 inhibition may represent a treatment option to reduce the progression of vascular calcification promoted by hyperglycemia in diabetes mellitus." (PMID 33003561, 2020). "Thus, SGK1 inhibition may reduce the development of vascular calcification promoted by hyperglycemia in diabetes." (PMID 33003561, 2020). "Moreover, increased Sgk1 expression in diabetes appears to be kidney-specific." (PMID 24827579, 2014). "Activation of AGC kinase members such as serum/glucocorticoid-regulated kinase 1 (SGK1), Akt, and PKC is regulated by mTOR, and these enzymes are relevant in case of apoptosis, cancer, and diabetes." (PMID 40148800, 2025). "Inhibition of SGK1 expression by siRNA decreased and ENaC and Na+/H+ exchanger isoform 1 (NHE1) expression was confirmed as significantly reduced as siSGK1 in the diabetes+dapagliflozin group." (PMID 36068525, 2022). "The RT-PCR showed a significant reduction in SGK1, ENaC, and NHE1 levels in the diabetes + dapa group compared to that in the diabetes group (P < 0.01, P < 0.05) and similarly tend to decreased expression level in Western blot." (PMID 36068525, 2022). "Thus, SGK1 inhibition may have overall beneficial effects during disease progression in diabetes." (PMID 33003561, 2020). "The described results propose a novel protective role of SGK-1 against apoptosis induced by ceramide and TNF-α, increasing our knowledge in this field, opening new perspectives to counteract cellular and tissue injuries, which are typical of several diseases like diabetes and its complications." (PMID 26379195, 2015). "By demonstrating an EMPA-mediated inhibition of IL-1β-induced SGK1 expression, this effect might be a potential explanation for the positive clinical effect seen with the use of SGLT2i in CKD patients irrespective of the presence and absence of diabetes." (PMID 34064989, 2021).
depression (23 papers, 2011 to 2025). "Elevated SGK1 expression has been associated with increased anxiety- and depression-like behaviors in mice, necessitating further research to ascertain if chronic gadolinium retention affects mood." (PMID 39792203, 2025). "SGK1, significantly associated with depression, is a mediator for cortisol effects on neurogenesis and GR function." (PMID 38745947, 2024). "In a mouse model of depression, corticosterone-induced reduction in the number of hippocampal astrocytes was found to be caused by SGK1, and electroconvulsive therapy inhibited SGK1 expression and promoted the occurrence of antidepressant behavior." (PMID 39737082, 2024). "This indicates that the SNPs of rs2910164 in the microRNA146a gene, the SNPs of rs2285666 in the ACE2 gene, the SNPs of rs1743963 and rs1763509 in the SGK1 gene are risk factors for the development of coronary heart disease and depression." (PMID 38745947, 2024). "The indicates that the SNPs of rs2910164 in the microRNA146a gene, rs2285666 in the ACE2 and rs1743963 and rs1763509 in the SGK1 gene are risk factors for the development of coronary heart disease and depression." (PMID 38745947, 2024). "We only found a significant decrease in mRNA levels of SGK-1 in the cortex of obese animals, a gene known to counteract the cortisol-induced reduction in neurogenesis a process associated with depression." (PMID 34714995, 2021). "In view of the complex relationships between SGK1, CHD, and depression, SGK1 is likely to be a potential co-pathogenic gene underlying susceptibility to CHD with depression." (PMID 31632443, 2019). "Overall, our study demonstrates for the first time the importance of SGK1 variants in the development of depression in CHD patients." (PMID 31632443, 2019). "Compelling evidence suggests that increased SGK1 expression or function is related to the pathogenic stress hypothesis of major depression." (PMID 32849818, 2020). "The inflammation resulting from physical stress has shown, at least in rats, to be associated with depression in presence of elevated levels of SGK1, both in blood and in hippocampal and amygdala neurons, within the framework of glucocorticoid-dependent depressive effects." (PMID 32849818, 2020). "Vice versa, the depression resulting from post-traumatic stress such as childhood and adolescent maltreatments is associated with a strong inflammatory component in the presence of decreased levels of SGK1, accompanied by reduced hippocampal neurogenesis." (PMID 32849818, 2020). "In conclusion, the present study supports the hypothesis that SGK1 polymorphisms contribute to the susceptibility to depression in CHD patients of the Chinese Han population." (PMID 31632443, 2019). "Thus, additional association studies investigating SGK1 diversity and susceptibility to depression in CHD patients are also required to replicate the associations." (PMID 31632443, 2019). "Thus, to further evaluate the role of SGK1 single-nucleotide polymorphisms (SNPs) in susceptibility to CHD with comorbid depression, we carried out a case–control study involving 257 CHD patients with or without depression and 107 controls." (PMID 31632443, 2019). "Considering that the interactions between various genes and/or environmental factors play a part in the effects of SGK1, the association between SGK1 polymorphisms and depression in CHD patients is likely to be confounded by various potential gene–gene and/or gene–environment interactions." (PMID 31632443, 2019). "Further examples include the hypoxia inducible factor 3 alpha subunit (Hif3a), whose expression was found to be increased in schizophrenic and bipolar patients or Sgk1 and Tsc22d3, which were associated with high interleukin (IL)-6 levels in patients suffering from the major depressive disorder." (PMID 27188165, 2016).
depression (continued). "SNPs of the microRNA146a gene at rs2910164, the ACE2 gene at the rs2285666 and the SGK1 gene at rs1743963 and rs1763509, and the SNPs at the 5-HTTLPR and BDNF gene loci are associated with the onset of comorbid depression in coronary heart disease." (PMID 38745947, 2024). "The results of the study showed that SNPs of eNOS, HSP70, FKBP5, miR-146a, ACE2, MAS1, SGK1, IL-4–589, IL-6–174, TNF-α–308, CRP–717, 5-HTTLPR, and BDNF genes are associated with the comorbidity of coronary heart disease and depression." (PMID 38745947, 2024). "It has also been shown that the level of SGK1 in the peripheral blood of patients with depression increases, and CORT reduces neuronal differentiation through SGK1-dependent mechanisms." (PMID 36844911, 2022). "Compelling data suggests that SGK1 is involved in the GC-induced reduction in the proliferation and differentiation of human hippocampal progenitor cells and that increased SGK1 expression or function is related to the pathogenic stress hypothesis of major depression." (PMID 34358084, 2021). "Recently, many studies have focused on the novel role of SGK1 in stress, depression, fear episodes, and anxiety." (PMID 34093127, 2021). "It is also an interesting fact that among the genes often related to depression in the literature, only mRNA levels of the SGK-1 gene were decreased in the PFC of obese animals." (PMID 34714995, 2021). "Taken together, these findings suggest that baicalin counteracts anxiety/depression-like behaviors, promoting hippocampal neurogenesis through the regulation of SGK1- and FKBP5-dependent GR phosphorylation." (PMID 32849818, 2020). "The role of neuro-inflammation in depression and consequently, the role of SGK1 in this specific phenotype is, in some ways, controversial." (PMID 32849818, 2020). "Under these specific conditions, the trend of SGK1 appears paradoxical with respect to that observed in the classic stress-dependent forms of depression." (PMID 32849818, 2020). "Accumulating evidence also suggests that SGK1 participates in the occurrence of depression via the glucocorticoid and brain-derived neurotrophic factor (BDNF) signaling pathway." (PMID 31632443, 2019). "As the downstream target molecule of the glucocorticoid receptor (GR), SGK1 is involved in the development of depression via the glucocorticoid signaling pathway." (PMID 31632443, 2019). "There is also growing evidence indicating that SGK1 stimulates the production of pro-inflammatory cytokines and oxidants, which are also closely related to depression." (PMID 31632443, 2019). "SGK1 is also involved in depression by modulating the effects of GCs on neurogenesis and glucocorticoid receptor function." (PMID 31540539, 2019). "A recent report describes the role of SGK1 in cortisol-induced reduction of progenitor cell proliferation in the hippocampus and enhancing GR function, both of which would be relevant to depression." (PMID 26506154, 2015). "To investigate the effects of SGK1 on rodent behavior, we used a rat inescapable stress paradigm that has been employed in rodent studies of depression but that also models some features of PTSD." (PMID 26506154, 2015). "In summary, this study demonstrates that SNPs of the microRNA146a gene at rs2910164, ACE2 gene at rs2285666 and the SGK1 gene at rs1743963 and rs1763509, and the SNPs at the 5-HTTLPR and BDNF gene loci are associated with the onset of comorbid depression in coronary heart disease." (PMID 38745947, 2024). "Considering the complicated relationship among SGK1, CHD, and depression, it is reasonable to propose that SGK1 may be a co-pathogenic gene in the comorbid mechanism of CHD and depression." (PMID 38745947, 2024). "Furthermore, cortisol secretion is increased in patients with depression, and local cortisol production in the oral mucosa upregulates serum glucocorticoid-regulated kinase-1 (SGK-1) expression." (PMID 38137013, 2023).